CD5 (CD5 molecule)
Diseases named in the same sentence as CD5 in open-access papers (continued):
Sharing a sentence is not in itself a finding about the gene and the disease.
cancer (continued). "As CD5 is not cancer specific, this treatment results in T cell aplasia." (PMID 30031396, 2018). "Interestingly, we observed not only an overall increase in CXCL9 in cancer, but also a significant increase in ER‐negative subtypes compared to luminal A cancers, and these levels correlated significantly with levels of the TIL‐related markers CD8A, CD4, and CD5." (PMID 30019538, 2018). "Our study shows that increasing the circulating/local levels of a soluble form of human CD5 (shCD5) might result in both specific and non-specific enhancement of immune responses to cancer cells." (PMID 29296231, 2017). "Therefore, our data support a role for CD5/CD5L interactions in the homeostasis of some lymphocyte populations with regulatory and/or effector function, while highlighting the potential use of targeting CD5 as an immunomodulatory strategy in cancer therapy." (PMID 24454761, 2014). "Two patients with negative CD5 expression were positive for CK5/6 and p63 but negative for TTF-1, presented with typical carcinoma showing thymus-like differentiation of the thyroid gland morphologically." (PMID 41278290, 2025). "Immunophenotypically, atypical CLL differs from classic CLL in the lack of expression of one or fewer surface antigens, most commonly CD5 and CD23, and the patient does not meet the criteria for a diagnosis of any other B-cell lymphoid malignancy." (PMID 37760396, 2023). "As CD5 and POU2F3 stained only CD117 positive carcinomas, and therefore would not improve sensitivity over that of CD117, they are not included in our recommended panel." (PMID 37190202, 2023). "In the xenograft mouse model established by SUP-T1 cells with moderate CD5 expression, after infusion of 2 × 106 CAR+ T cells per mouse, H65 and FHVH3 CAR-T cells temporarily inhibited and controlled cancer progression but failed to eradicate neoplastic cells." (PMID 34274536, 2021).
infection (62 papers, 2004 to 2025). The state of being infected such as from the introduction of a foreign agent such as serum, vaccine, antigenic substance or organism. "Consistent with that view, infection of LAT‐deficient DN3 γδint cells with LAT‐expressing retrovirus induced the surface expression of CD5 and of high levels of γδ TCR as observed on a fraction of WT DN3b γδ+ cells." (PMID 35128689, 2022). "In the T. gondii model, one study suggested that primed CD5+ B-1(a) cells can rescue B-cell-deficient mice during primary infection with a low virulence strain." (PMID 34871323, 2021). "Given that the strength of these tonic TCR interactions with self‐pMHC influence T‐cell function, it is possible that differences in CD5 levels on neonatal versus adult T cells explain, in part, some of the differences in their T‐cell response that render neonates more susceptible to infection." (PMID 33682083, 2021). "Notably, EomesCKO cells expressed higher levels of T-bet early after infection and higher levels of CD5, a marker previously associated with high affinity." (PMID 32182234, 2020). "Following the discovery of CD5 as a β-glucan PRR, CD5-deficient (cd5−/−) mice demonstrated higher susceptibility to systemic fungal (i.e., Candida albicans and Cryptococus neoformans) infection concomitant with lower pro-inflammatory cytokine production and T and B cell activation." (PMID 33287301, 2020). "CD5- and CD7-directed chimeric antigen receptor T-cell (5CAR and 7CAR) therapies for T-cell malignancies carry the risk of life-threatening infection." (PMID 41290542, 2025). "The CD5+ subset of cDC2 cells was found to have a greater ability to migrate to sites of infection compared to the CD5- subset; however, they produced a suppressive T cell phenotype, whereas CD5- cells elicited a stronger cytotoxic T cell effect." (PMID 37928547, 2023). "Collectively, these roles suggest that CD5+ B cells would be advantageous to the host in response to infection." (PMID 36477266, 2022). "CD5+ B-1 cell-derived NAbs have a unique germline-like structure that lacks N-additions, a feature critical for providing protection against infection." (PMID 36713434, 2022). "Infection of cattle with MAP resulted in increased CD5+ B cells, particularly the B-1a B cell subpopulation, aligning with results noted for other infectious pathogens in cattle." (PMID 36477266, 2022). "We observed that infection of Balb/c mice with P. yoelii I 7XL was lethal, and a rapid increase in dynamics of IL-10 producing B220+CD5+CD1d+ regulatory B cells over the course of infection was observed." (PMID 35625397, 2022). "Recent findings have shown that CD5 expression on B1 B cells drastically changes their ability to fight infection." (PMID 35327505, 2022). "Although a CD5- B cell subpopulation (B-1b) is present as well, it is considered a minor cell population and has less relevance for fighting infection." (PMID 36477266, 2022). "CD5+ B cells also are considered an innate-like B cell population that can act as antigen-presenting cells, rapidly producing antibodies in response to infection." (PMID 36477266, 2022). "Within the peritoneal B-1 cell compartment (CD19+ B220int CD11b+) increased percentages of CD5- B-1b cells were observed during secondary infection in A/J mice, which appear to have downregulated their BCR as evidenced by being IgMlo." (PMID 34871323, 2021). "We also observed an increase in LD Neu population expressing PD-L1 and CD5 markers from early to late active infection but decline in late convalescence." (PMID 34867943, 2021). "Germline transcription of Ighg1, Ighg3, Ighg2b, and Ighg2a/c was greatly enhanced in CD5- B-1b cells from A/J compared to C57BL/6J mice on day 5 of secondary infection, suggesting heightened isotype class switching occurred in mice in the resistant background." (PMID 34871323, 2021).
infection (continued). "Although both B1a and B1b cells have been reported to produce IgM in response to infection, it is becoming clear that CD5 expression cannot adequately describe the functional plasticity and heterogeneity of B1 cells." (PMID 34449811, 2021). "CD5 has been identified as essential for infection of T cells with native, patient-derived HCV, enabling a lymphoid reservoir." (PMID 33287301, 2020). "Infection with Ad-CD5 successfully restored the expression of CD5 in CD5-/- BMDC to levels higher than endogenous CD5 on WT BMDC." (PMID 31491023, 2019). "(D, right) Mice were grouped by initial percentage of CD5+ and CD5- B-1 cells (left) and % MedLN CD5+ B-1 cells present on days 0 (initial %) and 7 of infection were plotted with a line of best fit." (PMID 31433296, 2019). "Previously, established B cell lines were developed from in vitro infection of these cells (CD5 and CD21) with T. annulata sporozoites for the identification of various cell surface markers." (PMID 31052316, 2019). "The low-affinity RF is produced by CD5-expressing B cells, called B1a-B cells, in healthy subjects or patients with infection." (PMID 29262790, 2017). "It was already known that neonatal mice display an increased production of IL-10 early in the course of infection with Lm and after CpG stimulation, but the source of IL-10 in these neonatal studies had been shown to be macrophages and CD5+ B cells." (PMID 27074026, 2016). "In immunophenotypic CVL studies, increases in CD5+ T lymphocytes and subsets of CD4+ and CD8+ T lymphocytes were reported and related to a profile associated with possible resistance against infection by L. infantum." (PMID 24507702, 2014). "Mirsky and coworkers reported that the infection rate was approximately 40-fold higher for CD5+ B cells than for CD2+ T cells (121 ± 244 for CD5+ B cells and 3 ± 6 for CD2+ T cells), suggesting that B cells are the only PBMCs significantly infected by BLV." (PMID 23641811, 2013). "A lymphocyte-specific CD5 molecule was recently identified as essential for infection of T cells with native, patient-derived HCV." (PMID 23626783, 2013). "In contrast, CD5 mRNA level was significantly (P = 0.01) augmented in infected cells, while that of SR-B1 remained unchanged following infection (P = 0.54)." (PMID 23626783, 2013). "The expression of the CD5 cell surface marker did show a gradual change during the course of early infection." (PMID 19784370, 2009). "Early-gestation infection was associated with increased levels of eight inflammatory biomarker, including TNSF14, TGF-α, EN-RAGE, and decreased IL-18 levels, while late-gestation infection was linked to elevations in 12 biomarkers, including CD5, CD6, PD-L1." (PMID 41510260, 2025). "LTB had a different profile of CD5+ and CD10+ B cell subsets compared to ATB, suggesting that both B cell subsets could be associated with the infection state by Mtb." (PMID 37375508, 2023). "Natural antibody (NAb) derived from CD5+ B-1 cells maintains tissue homeostasis, controls inflammation, aids in establishing long-term protective responses against pathogens, and provides immediate protection from infection." (PMID 36713434, 2022). "Results showed that the size and weight of the thymus and the number of thymocytes were remarkably reduced in mice starting at week 5–6 after infection, accompanied by an aberrant development of T cells, reduced expression of CD5, and decreased proliferation of naive T cells." (PMID 36371464, 2022). "CD5 has also been shown to promote infection by the hepatitis C virus, indicating that the blockade of CD5 may be beneficial in treating certain chronic infections." (PMID 35327505, 2022). "CD5+ PD-L1+ regulatory B cells contract during early response to infection." (PMID 36300787, 2022). "This may be because EBV activates B lymphocytes upon infection, leading to increases in the abundances of their activator antigens CD5, CD80, and CD86, which play major roles in maintaining immune stability." (PMID 32149157, 2020).
infection (continued). "Similarly, CD5- B-1b cells were shown to expand and secrete protective IgM after infection with Borrelia hermsii and Salmonella typhimurium." (PMID 31433296, 2019). "We therefore aimed to reexamine whether activation and differentiation of CD5+ B-1 cells into CD5- IgM ASC were more universal outcomes of CD5+ B-1 cell activation to infections." (PMID 31433296, 2019). "Furthermore, FACS-sorting and culture of CD5+ and CD5- B-1 cells showed that a higher frequency and total number of CD5- B-1 cells secreted IgM in the MedLN compared to CD5+ B-1 cells on days 3, 5, and seven after infection." (PMID 31433296, 2019). "Furthermore, a single dose (10 μg/g body weight) of plant-produced cD5 mAb offered 100% protection against infection in mice after a lethal EV71 challenge." (PMID 31805650, 2019). "MedLN of mice reconstituted with mostly CD5- B-1 cells had reduced MedLN B-1 cell after infection." (PMID 31433296, 2019). "Importantly, prophylactic infusion of soluble CD5 or CD6 significantly ameliorated the infection outcome in the mouse model of secondary cystic echinococcosis." (PMID 30500820, 2018). "Importantly, the infusion of soluble forms of CD5 or CD6 improve infection outcomes in a murine model of secondary cystic echinococcosis." (PMID 30500820, 2018). "Furthermore, the Physical well-being subscale also demonstrated a corrected item-total correlation of 0.08 for the item I worry about spreading the infection (CD5), but if the item was deleted, the Cronbach’s alpha coefficient increased to 0.75." (PMID 28372548, 2017). "Not only the percentage of IL-17A+ in CD19+ B cells, but also of its subgroups, including CD1dhighIL-17A+, CD1dlowIL-17A+, CD5+IL-17A+, CD5−IL-17A+, CD1dhighCD5+IL-17A+, CD1dhighCD5−IL-17A+, CD1dlowCD5+IL-17A+, and CD1dlowCD5−IL-17A+, were elevated post-infection." (PMID 28732522, 2017). "We found that infection with T. spiralis led to a marked increase in the proportion and number of nTh1 cells in the thymus that was coincident (17 dpi) with a robust Th2 response, with lower level expression of CD5." (PMID 28406139, 2017). "Presumably, during an infection, there will be a large number of foreign antigens presented to T cells, which in turn will have been selected on a wide variety of self-antigens during thymic development and will therefore express varying levels of CD5." (PMID 26697015, 2015). "As well, HCV infection of T cells requires surface expression of CD5, and transfection of HCV non-susceptible T cell lines with CD5 renders these cells susceptible to infection." (PMID 26084511, 2015). "This resulting cell death may also be a reason for up-regulation of CD5 expression during the early stages of infection." (PMID 19784370, 2009). "By 6 hours post-infection only 28% of the GFP positive cells were expressing CD5." (PMID 19784370, 2009). "The CD5+ B-1a cells in the naturally infected cows shifted from a CD5+dim population to an increase in CD5+bright B cells, suggesting that this transition may be reflective of a regulatory mechanism during progression of infection." (PMID 36477266, 2022). "The number of mRNA copies of the B-cell-related genes Pax5, CD5, and CD19; T-cell-related gene CD8A; and MHC-related genes CIITA, HLA-DQ1, HLA-DR, and HLA-DO were significantly decreased in patients with infections." (PMID 40185975, 2025). "CD5 and CD6 were the ones showing the maximum variation in expression levels in primary cells after infection." (PMID 34983375, 2022). "Infections as diverse as Trypanosoma congolense, mycobacteria (MAP), and bovine leukosis virus (BLV) have resulted in increased numbers of CD5+ B cells in cattle." (PMID 36477266, 2022). "In the early phase after FCV Challenge I, all lymphocyte subsets (CD4+, CD8+, CD45R/B220+, CD5+, and CD5+/MHCII+) in all cats decreased in absolute numbers and returned to the preinfectional level by day 22 after challenge infection, except for CD4+/CD25+." (PMID 34578316, 2021).
infection (continued). "The percentage of all T lymphocytes (CD5+), as well as of CD4+ Thelper cells and CD8+ Tcytotoxic cells, decreases after infection with HA- strains, but increase slightly after infection with HA+, starting 4–8 h p.i.." (PMID 33805607, 2021). "Instead, a high proportion of immature/naïve CD5+ B cells might be a biomarker that reflects a less mature and activated humoral immune system in general among boys, which in turn could influence the magnitude of both infection- and vaccine-induced antibody responses." (PMID 29138503, 2017). "However, the association between EBV infection and CD5 down-regulation could actually reflect direct infection of the CD8+ T cells with EBV rather than the immune response against EBV." (PMID 25237383, 2014). "Both IL-10-producing CD5+ B cells and FoxP3+ TREG cells are stimulated by infection with schistosomes." (PMID 23429492, 2013). "We used a panel of surface antigen markers CD5, CD10, CD19, CD23, CD39, CD40 & CD44 and the intracellular marker Ki-67 to correlate B-cell activation with proliferation during the early stages of infection up to 7 days." (PMID 19784370, 2009). "The involvement of CD5 and VPS37C suggests that long COVID may be influenced by sustained immune dysregulation after the initial infection." (PMID 41009814, 2025). "The results from the current study showed a rapid expansion of B220+CD5+CD1d+ IL-10 producing regulatory B cells during infection with both lethal strain P. yoelii 17XL and non-lethal P. yoelii 17XNL at an early stage of infection." (PMID 35625397, 2022). "This diverse subset of B cells is characterized by the expression of CD5 and has been shown to secrete high levels of immunoglobulin M (IgM) in the absence of infection or vaccination." (PMID 35558082, 2022). "Sorted CD5+ cells did not secrete measurable amounts of IgM unless harvested after day 5 of infection." (PMID 31433296, 2019). "Infection of CD5-/- BMDC with Ad-GFP did not have a significant effect on cytokine production compared to control CD5-/- BMDC." (PMID 31491023, 2019). "Surprisingly, the absence of CD5 on the LLO56 background (LLO56/CD5−/−) does not change its apoptotic phenotype at day 7 post-infection, in our transfer system (unpublished observations)." (PMID 26697015, 2015). "Expression of the CD5 and CD11b cluster of differentiation markers has been associated with BLV-infection, although B lymphocytes negative for these receptors are also less efficient targets for the virus." (PMID 15462678, 2004). "Namely, CD5, CD8A, CD6 and CD244, C-C and C-X-C motif chemokines (CXCL5 CXCL6, MCP-4, and CCL20), as well as CD40, PDL-1, CUB domain-containing protein 1 (CDCP1) and interleukin-12B (IL-12B) were elevated in the late infection group compared to the unexposed group." (PMID 41510260, 2025). "Therefore, CD5+CD7+ ILCs could act as sentinels, patrolling the body via the blood vessels, and migrate “on-demand” into tissue during infection and other immune challenges." (PMID 34867984, 2021). "B1 cells are the main source of natural IgM and provided the first line of defense against infection, which account for approximately 5% to 10% of the total number of B cells, and can be subdivided into B1a (CD19+ CD11b+ CD5+) cells and B1b (CD19+ CD11b+ CD5-) Cells." (PMID 34788282, 2021). "In fact, chimeras generated with CD5- B-1 cells showed no more B-1 derived IgM ASC in their MedLN than uninfected chimeras, consistent with their previously reported deficiency in entering the MedLN after infection." (PMID 31433296, 2019). "This differential effect of HCV infection on the expression of CD81, OCLN and CD5, but not SR-B1 gene, provided supporting evidence that the respective proteins might be engaged in the infection process induced by HCV in T cells." (PMID 23626783, 2013).
infection (continued). "Therefore, vascular CD5+CD7+ ILCs may perform similar functions to blood monocytes that patrol blood vessels and gain access to tissue niches during altered organ homeostasis, when they differentiate into tissue-resident macrophages to support host defense against infection." (PMID 34867984, 2021). "Knocking-down OCLN in virus-prone T cell line inhibited HCV infection, while de novo infection downregulated OCLN and CD81, and upregulated CD5 without modifying SR-B1 expression." (PMID 23626783, 2013).
hematological malignancies (8 papers, 2011 to 2025). "Studies have reported the activity of dual target CAR-T against T-lymphocyte hematologic malignancies, such as CD5/CD7 CAR-T cells." (PMID 39845313, 2024). "The efficacy of adoptive transfer of CD5 CAR-NK cells warrants further efforts to clinical application for patients with T-cell hematologic malignancies in a clinical trial setting." (PMID 39462383, 2024). "Alternative CAR targets were explored in the treatment of hematological malignancies such as CD3, CD5, CD7, CD33, CD138, SLAMF7 and NKG2D ligands in pursuit of for more effective strategies." (PMID 39633491, 2024). "Additionally, several preclinical studies have shown that the genetic deletion of CD5 in CAR and TCR T-cells enhances expansion, persistence, and cytotoxicity in both solid tumor and hematological malignancy models." (PMID 39410047, 2024). "Moreover, in the case of hematological malignancies, the CD23-negative CD19+CD5+ cells are related to worse prognoses." (PMID 35456315, 2022).